RDM1 (RAD52 motif containing 1)
Description:
May confer resistance to the antitumor agent cisplatin. Binds to DNA and RNA.
Synonyms: RAD52B; MGC33977
Tractability: PROTAC: ubiquitination databases record sites on it.
Gene: Protein-coding gene on chromosome 17 (35,918,066 to 35,930,773, reverse strand). Ensembl gene ENSG00000278023.
Subcellular location: Nucleus; Cytoplasm; Nucleus, nucleolus; Cytoplasm (Isoform 1); Nucleus, PML body; Nucleus, Cajal body
Subcellular location (Human Protein Atlas): Nucleoli; Cytosol
Gene Ontology:
Molecular function: protein binding; nucleic acid binding; RNA binding
Cellular component: cytosol; nucleolus; Cajal body; cytoplasm; nucleus; PML body
Genetic constraint (gnomAD): Loss-of-function variants: 24 observed, 23.3 expected, observed/expected ratio (o/e) 1.03, 90% interval 0.75 to 1.45. The upper end of that interval is the gene's LOEUF score, 1.45, which puts it in group 5 of 6, group 1 being the genes least tolerant of losing a copy. Missense variants: 251 observed, 314.6 expected, observed/expected ratio (o/e) 0.8, 90% interval 0.72 to 0.89. Synonymous variants: 113 observed, 123.68 expected, observed/expected ratio (o/e) 0.91, 90% interval 0.78 to 1.07.
Homologues: Orthologues: chimpanzee RDM1 (99% identical), macaque RDM1 (96% identical), mouse Rdm1 (71% identical), rat Rdm1 (69% identical), rabbit RDM1 (63% identical), tropical clawed frog rdm1 (48% identical), zebrafish rdm1 (34% identical).
Diseases named in the same sentence as RDM1 in open-access papers:
RDM1 is named in the same sentence as 28 diseases in open-access papers, as found by Europe PMC text mining. Sharing a sentence is not in itself a finding about the gene and the disease. The quoted sentences say what the papers report.
hepatocellular carcinoma (6 papers, 2020 to 2026). A malignant tumor that arises from hepatocytes. "In clinical hepatocellular carcinoma (HCC) samples, low expression of RDM1 is associated with larger tumour size, poor tumour differentiation and unfavourable survival." (PMID 34264012, 2021). "Immunohistochemistry (IHC) method was used to detect the expression level of RDM1 in 90 cases of hepatocellular carcinoma and adjacent normal liver tissues." (PMID 34435618, 2021). "The results of the present study suggest that RDM1 is potentially a novel prognostic marker for different tumor types that can assess the level of immune cell infiltration, especially in hepatocellular carcinoma." (PMID 34435618, 2021). "We combined prognostic analysis and immune infiltration to comprehensively evaluate and judge the role of RDM1 in different cancers, with a focus on hepatocellular carcinoma." (PMID 34435618, 2021). "In conclusion, the present study jointly explores the role of RDM1 gene expression in hepatocellular carcinoma from the two aspects of immune cell infiltration and prognostic survival." (PMID 34435618, 2021). "The high expression of RDM1 is closely related to the prognosis of large logarithmic tumors, especially in patients with hepatocellular carcinoma, poorer OS and PFS, of which PFS is the most significant factor." (PMID 34435618, 2021). "As a result, the correlation between RDM1 and immune cell infiltration and clinical prognosis in hepatocellular carcinoma requires relevant basic experiments for validation." (PMID 34435618, 2021). "An increased correlation significance corresponded to a higher HR ratio, indicating that RDM1 expression is significantly up-regulated in patients with advanced hepatocellular carcinoma." (PMID 34435618, 2021). "In summary, these findings strongly suggest that RDM1 is a valuable prognostic marker for hepatocellular carcinoma." (PMID 34435618, 2021). "Additionally, this result reflects that high RDM1 expression is related to invasion and metastasis of hepatocellular carcinoma." (PMID 34435618, 2021). "Additionally, compared with the correlation of RDM1 expression of breast, stomach, lung or ovarian cancer, RDM1 expression and hepatocellular carcinoma have a higher prognostic HR value, and their correlation is more significant." (PMID 34435618, 2021). "In addition, our analysis showed that in hepatocellular carcinoma, the levels of immune infiltration and various immune markers are correlated with the expression level of RDM1." (PMID 34435618, 2021). "Loss of RAD52 motif 1 (RDM1), induced by methyltransferase‐like 3 (METTL3)‐mediated m6A modification, correlates with unfavorable clinical outcomes, promotes hepatocellular carcinoma (HCC) cell growth, and induces G2/M cell cycle arrest." (PMID 31670863, 2020). "We used the Oncomine, TIMER, GEPIA, Kaplan–Meier plotter and PrognoScan databases and other published literature to obtain relevant data on the role of RDM1 in hepatocellular carcinoma but did not verify the results through basic experiments." (PMID 34435618, 2021). "In patients with HCC, overexpression of METTL3 can reduce the expression of RDM1 in an m6A-dependent manner, promoting the survival, proliferation, and stability of hepatocellular carcinoma cells." (PMID 36230944, 2022). "In hepatocellular carcinoma (HCC), METTL3 has been shown to play a protumorigenic role by decreasing the level of RDM1, a key regulator of the DNA double-strand break repair and recombination, RNA processing and protein translation." (PMID 33814008, 2021).
lung carcinoma (5 papers, 2018 to 2021). "Finally, we further investigated the expression patterns of RDM1 in smokers since smoking is the leading risk factor of lung cancer." (PMID 30069034, 2018). "Excessive activation of RDM1 has been found to be involved in many human cancers, such as papillary thyroid carcinoma, neuroblastoma and lung cancer." (PMID 34264012, 2021). "The Oncomine data showed that RDM1 expression is up-regulated in colon cancer, breast cancer, gastric cancer, lung cancer, melanoma, ovarian cancer and prostate cancer compared with normal tissue." (PMID 34435618, 2021). "By comparing RDM1 gene expression between different cancer types and normal tissues using the Oncomine database, we showed that RDM1 is up-regulated in colon cancer, breast cancer, gastric cancer, lung cancer, melanoma, ovarian cancer and prostate cancer." (PMID 34435618, 2021). "It was found that RDM1 expression is related to ovarian cancer, bladder cancer, breast cancer, brain cancer and lung cancer." (PMID 34435618, 2021). "We therefore performed multiple Oncomine analyses in published datasets to examine the RDM1 levels in human lung cancer with various clinical characteristics 12–15." (PMID 30069034, 2018). "RAD52 motif‐containing 1 (RDM1), a key regulator of DNA double‐strand break repair and recombination, has been reported to play an important role in the development of various human cancers, such as papillary thyroid carcinoma, neuroblastoma and lung cancer." (PMID 34264012, 2021). "RDM1 was found to have function in lung cancer 16 and papillary thyroid carcinoma 17, but its function in NB progression remains unclear." (PMID 30868057, 2019). "First of all, analyses of human lung cancer samples had shown that RDM1 was over-expressed in lung adenocarcinoma tumors, initializing the hypothesis that RDM1 may impose an oncogenic function in lung cancer." (PMID 30069034, 2018). "But expression of RDM1 in lung cancer remains to be explored." (PMID 30069034, 2018). "Given the potential role of RDM1 in the DNA repair pathways that constitute an important aspect of cancer initiation and progression, we proposed that RDM1 might display oncogenic properties in lung cancer." (PMID 30069034, 2018).
breast carcinoma (3 papers, 2019 to 2021). "One component of the DNA damage repair pathway is RAD52 motif‐containing 1 (RDM1), but the specific role of RDM1 in breast cancer and the underlying mechanism remain unclear." (PMID 31222930, 2019). "Although there are few reports on the developmental role of RDM1 in tumors, studies have highlighted that RDM1 is up-regulated in papillary thyroid cancer, non-small cell lung cancer, ovarian cancer and breast cancer." (PMID 34435618, 2021). "In order to determine the function of RDM1, we detected the expression of RDM1 between breast cancer cells (MDA‐MB‐453, MDA‐MB‐231, HBL100 and MCF‐7) and normal cells (MCF‐10A)." (PMID 31222930, 2019). "Accordingly, in this study, we knocked down RDM1 in two breast cancer cell lines and evaluated the resulting cell proliferation and apoptosis as well as other cancer‐related phenotypes." (PMID 31222930, 2019). "Tumour sizes along the course of the in vivo growth were then recorded, revealing that RDM1 knockdown markedly decreased tumour size, weight and volume relative to the control group, confirming the oncogenic role of RDM1 in breast cancer progression." (PMID 31222930, 2019). "Accordingly, therapeutic targeting of RDM1 is a potential treatment strategy for breast cancer and overcoming drug resistance." (PMID 31222930, 2019). "Because disruption of RDM1 significantly disrupted proliferation in the breast cancer cells, we concluded that RDM1 positively regulates breast cancer cell proliferation." (PMID 31222930, 2019). "Taken together, RDM1 knockdown in breast cancer cells promoted cell cycle arrest as well as apoptosis, suggesting that RDM1 plays a positive role in cell viability." (PMID 31222930, 2019). "After confirming the role of RDM1 in breast cancer cell proliferation, we next examined the involvement of RDM1 in inducing apoptosis in breast cancer cells." (PMID 31222930, 2019). "In conclusion, this study offers important insights into the mechanism by which RDM1 is involved in breast cancer." (PMID 31222930, 2019). "To further uncover the oncogenic role of RDM1 in breast cancer cells, we injected the stable RDM1‐knockdown cell line derived from MCF‐7 cells into 6‐week‐old nude mice." (PMID 31222930, 2019). "Multiple Oncomine analyses of RDM1 expression levels in human breast cancer based on published datasets were conducted in order to determine whether RDM1 is involved in breast cancer progression." (PMID 31222930, 2019). "Interestingly, RDM1 was significantly overexpressed in breast cancer tissue relative to normal tissue." (PMID 31222930, 2019). "In addition, the in vivo growth of RDM1‐deficient cells was significantly repressed, suggesting that RDM1 is a novel oncogenic protein in human breast cancer cells." (PMID 31222930, 2019). "To determine whether RDM1 promotes cell growth in breast cancer cells, we performed a colony formation assay, which revealed that colony formation was significantly reduced in siRDM1‐expressing breast cancer cell culture or overexpression condition (G‐I)." (PMID 31222930, 2019). "The results showed that the expression of RDM1 was obviously increased in breast cancer cells." (PMID 31222930, 2019). "As disruption of DNA damage response signalling may impact the response to DNA‐damaging anticancer therapy, future research should determine whether DNA damage response pathways are altered in conjunction with RDM1 functionality in breast cancer cells." (PMID 31222930, 2019). "Finally, because our initial Oncomine analyses demonstrated that RDM1 is highly expressed in breast cancer samples from patients, we propose that RDM1 may be a potential prognostic breast cancer marker." (PMID 31222930, 2019). "Therefore, we predict that therapeutic targeting of RDM1 could be a promising strategy for clinical breast cancer therapy and overcoming drug resistance." (PMID 31222930, 2019).
breast carcinoma (continued). "Here, we examined the role played by RDM1 in breast cancer cell culture using the HBL100 and MCF‐7 breast cancer cell lines." (PMID 31222930, 2019). "In accord with this bioinformatics result, the immunohistochemical analysis of breast cancer samples revealed strong positive staining for RDM1 in tumour cells but not in normal tissues." (PMID 31222930, 2019).
glioma (3 papers, 2020 to 2021). A benign or malignant brain and spinal cord tumor that arises from glial cells (astrocytes, oligodendrocytes, ependymal cells). "In addition, compared with normal controls, RDM1 is down-regulated in brain cancer and other CNS cancers." (PMID 34435618, 2021). "Furthermore, we also measured the protein levels of four selected RBPs (GNL1, SPATS2L, RDM1, and FBXO17) in three glioma cell lines, one astrocytoma cell line (SW1088) and two glioblastoma cell lines (U251 and LN229)." (PMID 33634092, 2020).
papillary thyroid carcinoma (3 papers, 2019 to 2021). "In papillary thyroid carcinoma, RDM1 is up‐regulated, and RDM1 knockdown caused cell proliferation inhibition, cell apoptosis induction and cell cycle arrest in the G2/M phase." (PMID 34264012, 2021).
liver cancer (2 papers, 2020 to 2021). An epithelial or non-epithelial malignant neoplasm that arises from the liver. "In the Oncomine and PrognoScan databases, high RDM1 expression was associated with poor prognoses of ovarian, bladder, breast, brain, lung and liver cancer, ACC, KIRP and LGG." (PMID 34435618, 2021). "Among them, the expression of RDM1 and the prognosis of liver cancer increased with the increase in the LIHC stage and grade." (PMID 34435618, 2021). "The immunohistochemical staining score of liver cancer group was higher than that of adjacent cancer group (P<0.01), RDM1." (PMID 34435618, 2021). "The results showed that RDM1 expression was up-regulated in liver cancer tissues, and the immunostaining score was higher than that of adjacent tissues." (PMID 34435618, 2021). "The immunostaining status of RDM1 protein expression in liver cancer tissues and the staining status in adjacent tissues." (PMID 34435618, 2021).
lung adenocarcinoma (2 papers, 2018 to 2019). A carcinoma that arises from the lung and is characterized by the presence of malignant glandular epithelial cells. "Specifically, high RDM1 levels are significantly associated with advanced lung adenocarcinoma tumors, tumors from smokers, and patients of poor outcomes (i.e. short survivals and increased recurrence)." (PMID 30069034, 2018). "The findings, that RDM1 was over-expressed in lung adenocarcinoma and that high RDM1 was strongly associated with poor clinical outcomes, suggesting the oncogenic role of RDM1 in human lung adenocarcinomas." (PMID 30069034, 2018). "Based on these findings, we further examined whether higher expression of RDM1 levels were positively associated with various clinical outcomes in human lung adenocarcinoma." (PMID 30069034, 2018). "The resulting data support the previously identified oncogenic role of RDM1 in human lung adenocarcinoma." (PMID 31222930, 2019). "Our study links chemotherapeutic resistance to the involvement of RDM1 in lung adenocarcinoma oncogenesis." (PMID 31222930, 2019). "These in vitro and in vivo results conclude that RDM1 plays an oncogenic role in human lung adenocarcinoma." (PMID 30069034, 2018). "Knockdown of RDM1 in lung adenocarcinoma cells reduces cell proliferation and promotes apoptosis, consistent with the role RDM1 in the overexpression experiments." (PMID 30069034, 2018). "The lung adenocarcinoma patients with higher mRNA expression of RDM1 show the worse clinical outcomes." (PMID 30069034, 2018). "More interestingly, our initial comprehensive bioinformatics exploration in multiple Oncomine expression datasets has identified RDM1 as one of the significantly up-regulated genes in human lung adenocarcinoma." (PMID 30069034, 2018). "We observed that the mRNA and protein expression levels of RDM1 was up-regulated in human lung adenocarcinoma and correlated with poor clinical outcomes." (PMID 30069034, 2018). "In this study, we found that the mRNA and protein expressions of RDM1 were up-regulated in human lung adenocarcinoma samples." (PMID 30069034, 2018). "We knocked down and overexpressed RDM1 in two lung adenocarcinoma cell lines, PC9 and A549, and then evaluated cancer-related phenotypes, including cell proliferation and apoptosis." (PMID 30069034, 2018). "Consistent with the Oncomine results, our immunohistochemistry (IHC) and Western Blot analyses showed the protein level of RDM1 in human lung adenocarcinoma in increased compared to that of adjacent normal lungs." (PMID 30069034, 2018). "Here, we find that the mRNA and protein expression levels of RDM1 are significantly increased in human lung tumors, especially in lung adenocarcinoma." (PMID 30069034, 2018). "At the time of sacrifice, the shRDM1 tumors were significantly smaller compared with the tumors of the control group, confirming the oncogenic in vivo role of RDM1 in lung adenocarcinoma." (PMID 30069034, 2018). "As it has been proposed that combinatorial marker panel will out-perform any single marker for prognostic predictions, we propose that RDM1 can serve as an additional marker to the marker panel for the diagnosis and/or stratification for clinical management of lung adenocarcinoma." (PMID 30069034, 2018). "In summary, our study reveals the oncogenic function of RDM1 in lung adenocarcinoma." (PMID 30069034, 2018). "Interestingly, RDM1 is significantly over-expressed in lung adenocarcinoma and large cell carcinoma compared with the normal tissues." (PMID 30069034, 2018).